STK25 (serine/threonine kinase 25)
Diseases named in the same sentence as STK25 in open-access papers (continued):
Sharing a sentence is not in itself a finding about the gene and the disease.
liver cancer (3 papers, 2021 to 2022). An epithelial or non-epithelial malignant neoplasm that arises from the liver. "Interestingly, messenger RNA expression analysis in hepatic tumors from more than 350 subjects also has identified STK25 as an unfavorable prognostic marker in human liver cancer because high expression of STK25 was associated with a lower 5-year survival rate compared with low expression." (PMID 34624527, 2022). "This study provides an impetus for further analysis of STK25 as a therapeutic target in liver cancer." (PMID 34624527, 2022). "Our findings revealed that the expression of STK25 was higher in the liver cancer tissues compared with the paracancerous tissues." (PMID 34795841, 2021). "In line with the result of CCK8 assay, EdU assays indicated that STK25 knockdown markedly decreased the proliferation capacity of liver cancer cells." (PMID 34795841, 2021). "The findings manifested that STK25 knockdown significantly inhibited the proliferation, migration, and invasion capacity of liver cancer cells." (PMID 34795841, 2021). "Herein, we firstly constructed a prognostic model of ROS-related genes in HCC, and the role of STK25 in liver cancer was investigated using in vitro experiments." (PMID 34795841, 2021). "CCK8 assay revealed that STK25 knockdown significantly suppressed the proliferation of liver cancer cells." (PMID 34795841, 2021). "The analysis of public database data showed that STK25 was correlated with survival and prognosis of patients with liver cancer." (PMID 34795841, 2021). "While the role of G6PD in the HCC has been investigated, the role of STK25 in liver cancer is still unclear." (PMID 34795841, 2021). "Therefore, we would further study STK25 expression changes in clinical samples of liver cancer and explore the related mechanism." (PMID 35756606, 2022). "In vitro experiments were carried out to explore the role of STK25 in liver cancer." (PMID 34795841, 2021). "In this study, the role of STK25 in liver cancer was determined through in vitro experiments." (PMID 34795841, 2021). "In addition, transwell invasion assays were performed to estimate the invasion ability of cells, and the findings showed that STK25 knockdown significantly inhibited the invasion capacity of liver cancer cells." (PMID 34795841, 2021). "We further demonstrated the role of STK25 in liver cancer by performing in vitro experiments." (PMID 34795841, 2021). "We found that STK25 knockdown significantly increased the apoptosis of liver cancer cells." (PMID 34795841, 2021). "In addition, we preliminarily investigated the role of STK25 in liver cancer." (PMID 34795841, 2021). "Then, we also explored the correlation between the expression of 11 ROS-related genes and TNM stages in liver cancer, and the findings showed that the expression of CDKN2D, G6PD, MSRA, OXSR1, PFKP, and STK25 was connected with TNM stages (P < 0.05)." (PMID 34795841, 2021). "The results showed that STK25 expression was higher in liver cancer tissues compared with paired noncancerous tissues." (PMID 34795841, 2021). "However, there is still no report on the role of STK25 in liver cancer." (PMID 35756606, 2022). "However, as an ROS-related gene, the role of STK25 in liver cancer has not been reported." (PMID 34795841, 2021).
steatosis (3 papers, 2022 to 2025). Increased lipid within the cytoplasm of cells. "Consistently, the inhibition of STK25 or MST3 activity in obese mice by genetic ablation or antisense oligonucleotide (ASO) treatment effectively ameliorates steatosis, inflammatory infiltration, nutritional fibrosis, and hepatocellular damage in the liver compared with control mice." (PMID 40983918, 2025).
benign prostatic hyperplasia (2 papers, 2018 to 2019). A non-cancerous nodular enlargement of the prostate gland. "A previous study suggested that STK25 is highly expressed in prostate cancer, compared with benign prostatic hyperplasia, contributing to prostate tumorigenesis." (PMID 29996891, 2018).
Hyperglycemia (2 papers, 2020 to 2025). An increased concentration of glucose in the blood. "Furthermore, in addition to improved glucose tolerance and insulin sensitivity, as well as lower plasma insulin concentration detected in Stk25-KO mice in this study, we previously also observed reduced hyperglycemia in high-fat diet–fed Stk25–/– versus WT mice." (PMID 33170807, 2020).
neuroblastoma (2 papers, 2018 to 2022). Neuroblastoma (NB) is the most common solid, extracranial childhood tumor. "In addition, in neuroblastoma, the STK25 expression level correlates with the CCM2 and TrkA expression level, and patients with high STK25 expression have a better prognosis." (PMID 35756606, 2022).
atherosclerosis (1 paper, 2022). A disease characterized by the build-up of fatty material and calcium deposition in the arterial wall resulting in partial or complete occlusion of the arterial lumen. "Here we provide, to our knowledge, the first evidence for an essential cell-autonomous role of protein kinase STK25 in atherosclerosis susceptibility and show that antagonizing STK25 signaling in human aortic endothelial and smooth muscle cells is atheroprotective." (PMID 35440683, 2022). "We found that the genetic ablation of STK25 effectively attenuates the formation of atherosclerosis lesions in this model independently from alterations in circulating lipid levels." (PMID 35440683, 2022). "Future studies are needed to address the potential therapeutic relevance of pharmacological STK25 antagonism as a strategy to dampen or abrogate the development of atherosclerosis." (PMID 35440683, 2022). "The study provides mechanistic insights into our previous in vivo investigations in a mouse model of atherosclerosis, where genetic ablation of STK25 efficiently protected against the initiation and aggravation of aortic lesion formation." (PMID 35440683, 2022). "To decipher the cell-autonomous role of STK25 in the control of atherosclerosis, we here characterized the effects of STK25 inactivation in human primary aortic endothelial and smooth muscle cells." (PMID 35440683, 2022).
COVID-19 (1 paper, 2023). A disease caused by infection with severe acute respiratory syndrome coronavirus 2. "Analysis of the combined cohorts revealed elevated autoantibody responses against SPANXN4, STK25, ATF4, PRKD2, and CHMP3 proteins in COVID-19 patients." (PMID 37520825, 2023).
glomerulosclerosis (1 paper, 2020). A hardening of the kidney glomerulus caused by scarring of the blood vessels. "Notably, we found that glomerulosclerosis and tubulointerstitial fibrosis were markedly aggravated in Stk25 transgenic mice, as measured by immunofluorescence analyses of collagen IV and by Picrosirius red staining (labels both collagen I and -III)." (PMID 33170807, 2020).
Hepatic fibrosis (1 paper, 2022). The presence of excessive fibrous connective tissue in the liver. "Furthermore, HCC-bearing Stk25 knockout mice had reduced hepatic fibrosis as shown by reduced staining for collagen IV, Picrosirius Red (stains both collagen type I and type III), and fibronectin." (PMID 34624527, 2022).
hepatoblastoma (1 paper, 2025). Hepatoblastoma (HB) is a malignant hepatic tumor and is the most common pediatric liver cancer. "We generated stable knockout of STK25 in HepG2 (human hepatoblastoma cells) utilizing CRISPR/Cas9 technology and injected these cells subcutaneously into the flanks of high-fat diet-fed BALB/c nude mice." (PMID 40024534, 2025).
Intellectual disability (1 paper, 2023). "This deletion is within the region of 2q37 microdeletion syndrome characterized by microcephaly and intellectual disability, where STK25 was proposed to be a major contributor." (PMID 38098057, 2023).
liver disease (1 paper, 2024). "The results shed new light on the role of MST3, STK25, and MST4, as well as their interactions with PDCD10, MAP4K4, and HSD17B11, in the control of liver lipid homeostasis and metabolic dysfunction–associated steatotic liver disease susceptibility." (PMID 39395791, 2024).
liver dysfunction (1 paper, 2022). "However, plasma levels of ALT and AST can be difficult to interpret as these markers can be elevated in models of general liver dysfunction, thus readouts can be confounded by improvements in liver function due to ASO-mediated actions, as seen with ASOs targeting Stk25." (PMID 35295579, 2022).
medulloblastoma (1 paper, 2018). A malignant, invasive embryonal neoplasm arising from the cerebellum. "While the involvement of MST3/4 in CNS tumorigenesis still needs further investigation, another GCKIII family member, STK25, was shown to mediate TrkA-CCM2 death signaling in medulloblastoma cells." (PMID 29896440, 2018). "Subsequent findings show that STK25 can phosphorylate CCM2 and initiate death signaling in medulloblastoma cells." (PMID 29896440, 2018).
pancreatic cancer (1 paper, 2024). "In contrast, the survivalcurve is long-rank, with high expression of STK25 in pancreatic cancer,indicating that STK25 may have different functions depending on itsexpression in various cancers." (PMID 38293943, 2024). "Furthermore, it suggested that PROSER2 may inhibit the growthand metastasis of pancreatic cancer cells and regulate its mechanismthrough binding with STK25 and the PDCD10 complex." (PMID 38293943, 2024).
sarcoma (1 paper, 2019). A usually aggressive malignant neoplasm of the soft tissue or bone. "For example, STK25 is homozygously deleted in nearly 9% of all sarcomas." (PMID 30948712, 2019). "We assessed if STK25 deletion status has an effect on the clinical course of disease and found that sarcoma patients with STK25 deletions have significantly shorter durations of survival and that deletions of STK25 are more common in patients with recurrent disease than those without." (PMID 30948712, 2019).
tauopathy (1 paper, 2012). Neurodegenerative disorders involving deposition of abnormal tau protein isoforms (tau proteins) in neurons and glial cells in the brain. "To determine if Stk25 expression correlates with augmented Tau phosphorylation in disease conditions, we examined its expression in a tauopathy model mouse strain (Tg4510) that overexpresses human mutant Tau (P301L)." (PMID 22355340, 2012). "Furthermore Stk25 expression was not augmented in a tauopathy model mouse line." (PMID 22355340, 2012).
cancer (14 papers, 2018 to 2026). A tumor composed of atypical neoplastic, often pleomorphic cells that invade other tissues. "Loss of STK25, which is reported in many cancers, results in activation of YAP." (PMID 33557087, 2021). "Our data suggest that loss of STK25 may represent one route through which cancer cells functionally activate YAP/TAZ." (PMID 30948712, 2019). "Additionally, we found that this pattern of recurrent focal loss in human cancers is unique to STK25 among the currently identified LATS-activating kinases." (PMID 30948712, 2019). "Taken together, our findings suggest that loss of STK25 may be one mechanism through which human cancers functionally inactivate Hippo signaling to promote tumorigenesis and disease progression." (PMID 30948712, 2019). "Our data demonstrate that loss of STK25 represents one potential route through which cancer cells might deregulate the Hippo pathway to achieve pathologic capacity." (PMID 30948712, 2019). "STK25 is significantly focally deleted across a wide spectrum of human cancers, suggesting STK25 loss may represent a common mechanism by which tumor cells functionally impair the Hippo tumor suppressor pathway." (PMID 30948712, 2019). "According to the Human Cancer Database, focal deletion of STK25 is common in human cancers, such as cervical squamous cell carcinoma, urinary tract carcinoma, and head and neck squamous cell carcinoma." (PMID 35756606, 2022). "We found that increased STK25 expression in the livers of individuals with HCC was associated with the upregulated concentration of serum α-fetoprotein (AFP; a biomarker of a cancer-permissive tissue milieu) as well as advanced histologic grade and pathologic stage of the tumor." (PMID 40024534, 2025). "Using an additional database, we further grouped patients with high and low expression of STK25 in cancer tissue for prognostic analysis and obtained consistent results, again validating our hypothesis." (PMID 34986838, 2022). "According to the human cancer databases, focal deletion of STK25 is also very common in human cancers, such as cervical squamous cell carcinoma, bladder urothelial carcinoma, and head and neck squamous cell carcinoma, and it can be regulated by different mechanisms." (PMID 34986838, 2022). "Accordingly, high expression of STK25 may be associated with HCC patients and poor prognosis, which implicates STK25 could be a potential target for lipid metabolism in cancer therapy." (PMID 34986838, 2022). "Interestingly, bioinformatic analysis of TCGA reveals that focal deletion of STK25 is a common event across many tumor subtypes, with deep deletions occurring in a significant proportion of multiple aggressive cancers." (PMID 30948712, 2019). "The functions of STK25 in cancer development and progression are debated." (PMID 29996891, 2018). "Taken together, these findings suggest that STK25 could serve as a potential target in the treatment of cancers that correlate with dysregulated glycolysis that is induced by activation of mTOR signaling." (PMID 29996891, 2018). "However, the role of STK25 in aerobic glycolysis in cancer cells remains less well characterized." (PMID 29996891, 2018). "To understand whether this finding is also conserved across other cancer types, we used the entire Cancer Cell Line Encyclopedia mRNA expression dataset to obtain the co-expression of all the pairwise combinations of C4orf19, PDCD10, STK24, STK25, and STK26." (PMID 38517886, 2024). "Furthermore, the silencing of STK25 decreased the transcript levels of Slug and Zeb1, which are the critical transcriptional factors regulating EMT of cancer cells." (PMID 34624527, 2022). "This alternative mechanism provides some explanation for the robustness with which loss of STK25 is able to decrease LATS activation, and may also explain why STK25 is frequently focally deleted in a spectrum of human cancers, while MST/MAP4K pathway components are not." (PMID 30948712, 2019).
tumor (14 papers, 2018 to 2026). "Serine/threonine protein kinase 25 (STK25) has been previously implicated in the progression of various neoplastic diseases." (PMID 40729594, 2025). "Together, these results indicate that STK25 deficiency in hepatocytes protects against tumor development with suppression of several molecular signaling pathways typically activated in aggressive human HCC." (PMID 34624527, 2022). "To explore the mechanisms by which a depletion of STK25 exerts a tumor-mitigating effect, we first examined whether the loss of STK25 decreased the susceptibility of knockout mice to hepatocarcinogenesis by augmenting cell death." (PMID 34624527, 2022). "We found that the treatment with GalNAc-Stk25 ASO achieved similar effectiveness in reducing HCC tumor formation and growth compared with 4-fold higher doses of Stk25 ASO." (PMID 40024534, 2025). "Remarkably, the deletion of STK25 completely blocked in vivo tumor formation and growth ability of HepG2 cells, whereas all mice inoculated with wild-type HepG2 cells developed tumors of variable size." (PMID 40024534, 2025). "Considering that STK25 regulates hepatocellular lipid homeostasis, which is critical for tumor energy metabolism and biomass synthesis, we next studied mitochondrial and peroxisomal function in Hep3B cells." (PMID 40024534, 2025). "At the same time, STK25 plays an important role in energy metabolism and tumor genesis and development." (PMID 35265128, 2022). "Using mRNA-seq data from GEPIA, we reviewed STK25 expression in different organs in TCGA, including adjacent and tumor." (PMID 34986838, 2022). "Whereas downregulation of STK25 triggers a mechanism by which tumour cells functionally impair the hippo tumour tumour-suppressor pathway." (PMID 35057823, 2022). "Together, these results suggest that both tumor initiation and growth were affected by STK25 ablation." (PMID 34624527, 2022). "In order to more intuitively reflect the changes of lipid metabolism pathway and EMT after STK25 knockdown, the tumor tissues were also analyzed to evaluate the differences in STK25 and lipid metabolism." (PMID 34986838, 2022). "Here, the expression of STK25, tumor stem cell markers, EMT, and YAP/TAZ activity in HCC cells were detected when treated with exosomal miR-4800-3p or transfected with miR-4800-3p mimic or miR-4800-3p inhibitor, respectively." (PMID 35756606, 2022). "In agreement with the DEN-induced HCC model, the tumor load was reduced in livers from Stk25-/- vs wild-type mice, including a decrease in the maximal and total volume as well as the number of macroscopic HCC nodules." (PMID 34624527, 2022). "Taken together, the findings reveal a critical role of STK25 for regulating PD-L1 protein stability in tumor immune evasion, and suggest that targeting STK25 may provide a potential approach to increase sensitivity to the ICB treatment in patients with CRC." (PMID 40729594, 2025). "Here, it is demonstrated that STK25 global knockout (STK25-/-) mice and STK25-knockout tumor-bearing mice exhibited enhanced effectiveness of anti-PD-1 immunotherapy, which leads to significant tumor suppression with increased recruitment of CD8+ T cells." (PMID 40729594, 2025). "In other words, STK25 is closely related to tumor and energy metabolism." (PMID 34986838, 2022). "Using the DEN- and CDAA-induced models of HCC, we found that the livers from Stk25 knockout mice showed markedly lower tumor burden compared with wild-type littermates, which was accompanied by reduced apoptosis and compensatory cell proliferation, as well as suppressed neoangiogenesis." (PMID 34624527, 2022). "Previous studies have shown that STK25 could suppress tumor cell growth and proliferation by downregulating the Golph3-dependent mTOR pathway, promoting tumor cell apoptosis by regulating CCM2TrkA, etc.." (PMID 35756606, 2022).